NKX3-2 (NK3 homeobox 2)
Description:
Transcriptional repressor that acts as a negative regulator of chondrocyte maturation. PLays a role in distal stomach development; required for proper antral-pyloric morphogenesis and development of antral-type epithelium. In concert with GSC, defines the structural components of the middle ear; required for tympanic ring and gonium development and in the regulation of the width of the malleus (By similarity).
Synonyms: BAPX1; NKX3B; NKX3.2; SMMD
Tractability: No criterion of Open Targets' tractability assessment is met for any kind of drug.
Gene: Protein-coding gene on chromosome 4 (13,540,830 to 13,544,508, reverse strand). Ensembl gene ENSG00000109705.
Subcellular location: Nucleus
Subcellular location (Human Protein Atlas): Nucleoplasm
Pathways (Reactome):
Gene expression (Transcription): Regulation of RUNX2 expression and activity
Gene Ontology:
Molecular function: protein binding; sequence-specific double-stranded DNA binding; DNA-binding transcription factor activity, RNA polymerase II-specific; RNA polymerase II cis-regulatory region sequence-specific DNA binding; DNA binding; DNA-binding transcription repressor activity, RNA polymerase II-specific
Biological process: cell differentiation; negative regulation of chondrocyte differentiation; regulation of transcription by RNA polymerase II; skeletal system development; transcription by RNA polymerase II; negative regulation of transcription by RNA polymerase II; regulation of DNA-templated transcription
Cellular component: chromatin; nucleus
Genetic constraint (gnomAD): Loss-of-function variants: 13 observed, 17.17 expected, observed/expected ratio (o/e) 0.76, 90% interval 0.49 to 1.2. The synonymous counts are far from expectation, so gnomAD's model fits this gene poorly and the ratio says little. Missense variants: 562 observed, 415.17 expected, observed/expected ratio (o/e) 1.35, 90% interval 1.26 to 1.45. Synonymous variants: 269 observed, 196.35 expected, observed/expected ratio (o/e) 1.37, 90% interval 1.24 to 1.52.
Homologues: Orthologues: chimpanzee NKX3-2 (99% identical), macaque NKX3-2 (98% identical), rabbit NKX3-2 (91% identical), pig NKX3-2 (90% identical), dog NKX3-2 (89% identical), guinea pig NKX3-2 (86% identical), mouse Nkx3-2 (85% identical), rat Nkx3-2 (85% identical), zebrafish nkx3-2 (47% identical), Drosophila melanogaster scro (20% identical), Caenorhabditis elegans ceh-24 (17% identical), Caenorhabditis elegans ceh-28 (15% identical), and 4 more. Paralogues in human: NKX3-1 (27% identical), NKX2-6 (26% identical), NKX2-3 (25% identical), NKX2-5 (24% identical), NKX2-2 (22% identical), NKX2-4 (21% identical), NKX2-1 (21% identical), NKX1-1 (20% identical), NKX1-2 (20% identical), NKX2-8 (20% identical), NKX6-1 (16% identical), NKX6-2 (15% identical), and 1 more.
Diseases named in the same sentence as NKX3-2 in open-access papers:
NKX3-2 is named in the same sentence as 43 diseases in open-access papers, as found by Europe PMC text mining. Sharing a sentence is not in itself a finding about the gene and the disease. The quoted sentences say what the papers report.
spondylo-megaepiphyseal-metaphyseal dysplasia (5 papers, 2012 to 2023). "Absent vertebral body ossification and macrocephaly are found in Spondylo-megaepiphyseal-metaphyseal dysplasia, associated with biallelic variants in NKX3-2 (MIM# 613330)." (PMID 35096710, 2021). "In humans, homozygous frameshift mutations in NKX3-2 cause the rare disorder spondylo-megaepiphyseal-metaphyseal dysplasia (SMMD; OMIM: 613330), which is characterized by short-trunk, long-limbed dwarfism and bow-leggedness." (PMID 31169497, 2019).
gastric cancer (3 papers, 2023 to 2025). A primary or metastatic malignant neoplasm involving the stomach. "NKX3-2 is upregulated in chemoresistant ovarian tumors and metastatic gastric cancer cells; however, its prognostic role and mechanistic involvement in cancer cell biology remain to be elucidated." (PMID 40497941, 2025). "A few studies reported the involvement of NKX3-2 in promoting the migration and invasion of gastric cancer cells and the aberrant regulation of immune cell differentiation in B-cell lymphoma and T-cell acute lymphoblastic leukemia." (PMID 39513923, 2024). "NKX3-2 was shown to promote the migration of gastric cancer cells." (PMID 39513923, 2024).
ovarian carcinoma (3 papers, 2024 to 2025). A malignant neoplasm originating from the surface ovarian epithelium. "This implies that NKX3-2 could influence ovarian cancer cells’ susceptibility to paclitaxel." (PMID 40291779, 2025). "Taken together, these results indicate that GFPT2 influences the NF-κB pathway, at least partially, by regulating NKX3-2, providing fresh perspectives on the intricate signaling networks within ovarian cancer cells." (PMID 40291779, 2025). "Recent studies have underscored the role of NKX3-2 in ovarian cancer, demonstrating its potential to induce the migration of ovarian cancer cells." (PMID 40291779, 2025). "Recently, we have reported that NKX3-2 promotes ovarian cancer cell migration by downregulating autophagy through the modulation of lysosome transport." (PMID 40497941, 2025). "Bioinformatic analyses revealed that in ovarian cancer patients, the expression of NKX3-2 positively correlates with genes involved in cell motility and migration, while it negatively correlates with macromolecular catabolic pathways." (PMID 39513923, 2024). "In ovarian cancer cells, NKX3-2’s regulation of autophagy might affect the cells’ ability to withstand paclitaxel-induced stress, potentially aiding in cancer cell survival." (PMID 40291779, 2025). "Taken together, these data reinforce the view that NKX3-2 may represent an oncogenic factor for ovarian cancer patients." (PMID 40497941, 2025). "Interestingly, here we show that a low NKX3-2/highMAP1LC3B signature predicts better clinical outcomes for ovarian cancer patients." (PMID 40497941, 2025). "Our transcriptomic analyses performed in the TCGA ovarian cancer dataset revealed that NKX3-2 expression positively correlates with genes involved in cell locomotion, while negatively correlating with transcripts belonging to the proteolysis and macromolecule catabolic processes." (PMID 39513923, 2024). "Taken together, these data reveal the mechanism by which the LPA-NKX3-2 axis promotes the invasiveness of ovarian cancer cells and supports the possibility of targeting NKX3-2 to reduce the migratory capacity of cancer cells in response to a permissive microenvironment." (PMID 39513923, 2024).
ovarian carcinoma (continued). "Recently, we reported that NKX3-2 is one of the main downstream effectors of the signaling cascade induced by LPA, promoting ovarian cancer cell motility through the downregulation of autophagy." (PMID 40497941, 2025). "Transcriptomic and Western blotting analyses revealed NKX3-2, a transcriptional factor, to be among the genes hyperexpressed in LPA-stimulated ovarian cancer cells." (PMID 39513923, 2024). "Consistent with its pro-tumorigenic role in ovarian cancer, LPA seemed to favor the peripheral scattering of the lysosomes, which was abrogated upon the silencing of NKX3-2." (PMID 39513923, 2024). "Therefore, this study aimed to investigate whether and how NKX3-2 could mediate LPA effects on cell migration and autophagy in ovarian cancer cells." (PMID 39513923, 2024). "Remarkably, we observed that patients bearing a tumor with low NKX3-2 together with high MAP1LC3B levels (indicative of active autophagy) display a favorable clinical outcome, reinforcing the view that this signature may have translational relevance for ovarian cancer." (PMID 40497941, 2025). "Moreover, NKX3-2 expression is elevated in chemoresistant ovarian cancers as opposed to their chemosensitive counterparts, with high levels of NKX3-2 expression being significantly correlated with the occurrence of distant metastasis, which is consistent with our results from TCGA data analysis." (PMID 40291779, 2025).
Hypertension (2 papers, 2022). The presence of chronic increased pressure in the systemic arterial system. "At the same time, SIRT6 activity prevents hypertension and its renal complications by maintaining endothelial homeostasis through the induction of GATA-binding protein 5 (GATA5) via NK3 homeobox 2 (Nkx3.2) transcription inhibition." (PMID 35328633, 2022).
liver disease (2 papers, 2023 to 2025). "Further validation by qMSP in a larger cohort consisting of 54 non-cirrhotic HCC livers compared to 36 samples with non-cirrhotic liver disease showed higher methylation levels for all DMMs tested, except for NKX3-2 and GRASP." (PMID 40375278, 2025).
ovarian tumors (2 papers, 2024 to 2025). "Furthermore, NKX3-2 was found significantly upregulated in chemoresistant ovarian tumors compared to chemosensitive ones, and it correlated with distant metastasis." (PMID 39513923, 2024).
hepatocellular carcinoma (1 paper, 2024). A malignant tumor that arises from hepatocytes. "Additionally, NKX3-2 expression was positively correlated with tumor-associated macrophage infiltration in hepatocellular carcinoma, and this predicted a worse clinical outcome for those patients." (PMID 39513923, 2024).
microtia (1 paper, 2014). "Based on the knowledge that microtia is one of the facial deformities with cartilage abnormity, we suggest detailed investigations on the EVC, EVC2, SLC2A9, NKX3-2 and HMX1 genes for this isolated microtia pedigree." (PMID 24983964, 2014). "The EVC gene was selected for its roles in cartilage development, and the NKX3-2 and HMX1 gene was for their link to syndromic microtia." (PMID 24983964, 2014).
pancreatic carcinoma (1 paper, 2025). "The potential link between NKX3-2 and drug resistance is supported by research indicating that NKX3-2 is an EMT-related gene that may contribute to acquiring paclitaxel resistance in pancreatic carcinoma cells, suggesting its impact on chemotherapy response." (PMID 40291779, 2025).
cancer (6 papers, 2022 to 2025). A tumor composed of atypical neoplastic, often pleomorphic cells that invade other tissues. "Additionally, NKX3-2 silencing associates with the partial abrogation of LPA-induced cancer cell migration and the concomitant inhibition of autophagy, further consolidating the role of NKX3-2 as one of the main downstream effectors of the signaling cascade induced by LPA." (PMID 39513923, 2024). "By interrogating the TCGA database, we found that cancer patients with high NKX3-2 expression had a shorter overall survival rate than patients with low expression." (PMID 40497941, 2025). "The study revealed that NKX3-2 expression positively correlates with tumor-infiltrating immune cells, collectively accelerating cancer progression by promoting immune evasion." (PMID 40497941, 2025). "In cancer cells, NKX3-2 inhibits autophagy not only by negatively affecting late events, such as the fusion between autophagosomes and lysosomes, but also early events, such as mTOR recruitment to the lysosomal membrane and the autophagosome formation." (PMID 39513923, 2024). "Taken together, our data show that NKX3-2 promotes OC cell motility through the downregulation of autophagy, as the knockdown of the latter is able to partially restore the migration of cancer cells compared to the trend observed in the NKX3-2-silenced cells." (PMID 39513923, 2024). "A limited number of studies have reported the involvement of NKX3-2 in cancer progression." (PMID 40497941, 2025). "To determine whether NKX3-2 expression could have clinical relevance in cancer, we first focused on the prognostic value of NKX3-2 among various tumors interrogating the TCGA database." (PMID 40497941, 2025). "However, the mechanistic role of NKX3-2 in cancer biology has been poorly studied, and in few settings." (PMID 39513923, 2024). "However, the functional role of NKX3-2 in cancer cell biology has been poorly described so far." (PMID 40497941, 2025). "Additionally, an examination of the peritoneum and/or fallopian tube and a comparison of NKX3-2 expression in non-cancer patients (e.g., controls, subjects that undergo surgery for hysterectomy) and cancer patients are instrumental to strengthen the translational relevance of our findings." (PMID 40497941, 2025). "Taken together, our data indicate that NKX3-2 may harbor a promising potential as an oncogenic factor, thus prompting future studies to deeper elucidate its biological significance and potential as an anti-cancer therapeutic target." (PMID 39513923, 2024). "Our data may pave the way for future studies aimed at more deeply assessing its role in other cancer hallmarks, further providing a solid rationale to propose NKX3-2 as a novel therapeutic target in the tumors overexpressing NKX3-2." (PMID 39513923, 2024). "Understanding the complex interactions between GFPT2, NKX3-2, Caspases, and Bcl-2 family proteins may offer valuable insights into developing strategies to combat paclitaxel resistance in EOC, guiding the creation of novel therapeutic approaches for this challenging cancer." (PMID 40291779, 2025).
tumor (6 papers, 2019 to 2025). "Remarkably, patients bearing a tumor characterized by low NKX3-2 and high MAP1LC3B expression (indicative of active autophagy) display a better prognosis." (PMID 40497941, 2025). "In conclusion, NKX3-2 may represent a novel oncogenic factor contributing to tumor progression." (PMID 39513923, 2024). "Restoration of HDAC complexes in the condensates severely dampens the activation of SS18-SSX downstream genes such as PAX6 and NKX3-2 and almost abolishes the tumorigenicity of SS18-SSX tested by EdU cell proliferation assay, colony formation assay and tumor-bearing mouse models." (PMID 38678233, 2024).
skeletal dysplasia (4 papers, 2012 to 2022). Any Mendelian diseases that affects growth and development of the skeleton. "SMAD1 was one of the essential molecules in the BMP/SMAD pathway critical for bone metabolism, and NKX3‐2 was reported to relate with skeletal dysplasia." (PMID 35297204, 2022).
NKX3-2 also shares sentences with these, for which no sentence is quoted: asplenia (2 papers); breast invasive carcinoma (2); Cirrhosis (2); liver cancer (2); B-cell lymphoma (1); bladder urothelial carcinoma (1); brain glioma (1); cholangiocarcinoma (1); chronic hepatitis (1); co-infection (1); colorectal adenocarcinoma (1); dysplasia (1); fibrolamellar carcinoma (1); glioblastoma multiforme (1); Hip dysplasia (1); infection (1); kidney carcinoma (1); lung adenocarcinoma (1); lung squamous cell carcinoma (1); lymph node metastasis (1); melanoma (1); neuroblastoma (1); non-alcoholic fatty liver disease (1); Obesity (1); osteoarthritis (1); prostate carcinoma (1); rectal cancer (1); skeletal diseases (1); T-cell acute lymphoblastic leukemia (1); viral infection (1).
A further 1 disease shares a sentence with NKX3-2 in 1 paper.